RBFOX2 (RNA binding fox-1 homolog 2)
Diseases named in the same sentence as RBFOX2 in open-access papers (continued):
Sharing a sentence is not in itself a finding about the gene and the disease.
diabetes (8 papers, 2018 to 2025). "Polypyrimidine tract-binding protein 1 (PTBP1), CUGBP Elav-like family member (CELF) and RBFOX2 are associated with aberrant alternative splicing in diabetes." (PMID 35597446, 2022). "The latest studies noted that RBFOX2 is implicated in cardiac complications of diabetes: RBFOX2 regulates alternative splicing in diabetic heart disease by binding to the (U)GCAUG pattern in RNA." (PMID 35597446, 2022). "Besides Srrm4, the expression of two other neuron-specific splicing factors, Nova1 and Rbfox2, as well as the diabetes gene Glis3, which regulates splicing of Bim3, encoding an apoptosis protein, is lower in NZO than in B6-ob/ob islets." (PMID 34445304, 2021). "De novo mutations in Rbfox2 have also been identified in congenital heart disease, and alterations in Rbfox2 activity may be an early event in diabetes-induced heart pathology." (PMID 29293084, 2018). "In DHD, RBFOX2 expression is elevated in left ventricular cardiomyocytes of human patients with type 2 diabetes mellitus, and this upregulation coincides with increased expression of RBFOX2‐DN isoforms." (PMID 39243148, 2024). "Together these data support RBFOX2 as a strong candidate for regulating alternative splicing in diabetes and maintaining endocrine cell health and function." (PMID 38007492, 2023). "Increased CaV1.2E9* channels are found in diabetic heart, which is attributed by AGEs-induced downregulation of Rbfox2, and hyperpolarized window current of CaV1.2E9* channels make it easier to be opened at the potentials closer to resting membrane potential." (PMID 37415128, 2023). "Our analysis confirms Rbfox2 expression is decreased in mouse models and humans with diabetes and shows that many putative RBFOX2 targets are mis-spliced in disease." (PMID 38007492, 2023). "Together, our results showed that the AS of CaV1.2 channel can be dynamically regulated by Rbfox2 in cardiomyocytes, thus aberrant splicing of CaV1.2 is indeed attributed to dysregulated Rbfox2 in diabetes-induced cardiomyopathy." (PMID 37415128, 2023). "Dysregulation of RBFOX2 has been shown to be an early event in cardiac pathogenesis of diabetes in human." (PMID 34996843, 2022). "Our work elucidates the underlying mechanisms for CaV1.2 channel regulation in diabetic heart, and targeting Rbfox2 to reset the aberrantly spliced CaV1.2 channel might be a promising therapeutic approach in diabetes-induced cardiac hypertrophy." (PMID 37415128, 2023). "Despite the apparent normal formation of the pancreatic islets, intraperitoneal glucose tolerance tests (IP-GTT) showed that Rbfox2-mut mice were glucose intolerant as early as 4 weeks of age, although, similar to many mouse models of diabetes, the phenotype was more severe in male mice." (PMID 38007492, 2023). "In detail, AGEs-induced dysregulation of Rbfox2 yielded aberrant splicing of CaV1.2 channel, which hyperpolarized the window currents and increased intracellular calcium concentration ([Ca2+]i), and finally led to cardiac hypertrophy in diabetes." (PMID 37415128, 2023). "Therefore, targeting Rbfox2 to reset the aberrantly spliced CaV1.2 channel might be a promising therapeutic approach in diabetes-induced cardiac hypertrophy." (PMID 37415128, 2023).
dilated cardiomyopathy (6 papers, 2016 to 2024). Cardiomyopathy which is characterized by dilation and contractile dysfunction of the left and right ventricles. "In particular, mutations of RBM20 and RBFOX2 are associated with dilated cardiomyopathy, hypertrophic cardiomyopathy, or hypoplastic left heart syndrome." (PMID 38535111, 2024). "Rbfox1 also regulates splicing of a MEF2A exon in mouse and zebrafish heart that is mis-spliced in cells from human patients with dilated cardiomyopathy, and Rbfox1 and Rbfox2 cooperatively regulate splicing of Mef2D during C2C12 differentiation." (PMID 34996845, 2022). "In human hearts, we found that the mRNA level of splicing factor Rbfox1, but not Rbfox2, was downregulated in dilated cardiomyopathy, and CACNA1C mRNA level was dramatically decreased in the both of dilated and ischemic cardiomyopathy." (PMID 28949795, 2018).
glioblastoma (6 papers, 2021 to 2025). The most malignant astrocytic tumor (WHO grade IV). "Recent study featured sophisticated interplay of Ptbp1, Ptbp2, RbFox2, and SON (SON DNA and RNA binding protein) promoting glioblastoma multiforme (GBM) genesis." (PMID 35204777, 2022). "Here, we identify SON as a master regulator that activates PTBP1-mediated oncogenic splicing while suppressing RBFOX2-mediated non-oncogenic neuronal splicing in glioblastoma multiforme (GBM)." (PMID 34548489, 2021).
pancreatic cancer (6 papers, 2022 to 2025). "Our studies link RBFOX2-associated alternative splicing of ABI1 to pancreatic cancer progression." (PMID 38114498, 2023). "To further characterize RBFOX2 protein abundance in PDAC cell lines, we performed Western blot analysis of RBFOX2 protein abundance in a panel of pancreatic cancer cell lines and found RBFOX2 is present as two major isoforms of 47 kD and 53 kD." (PMID 38114498, 2023). "We detected enrichment for RHO GTPase pathway genes among the RBFOX2-regulated splicing targets and demonstrated their functional role in invasion by pancreatic cancer cells." (PMID 36949200, 2023). "Given the complex regulation of RBFOX2 at the RNA level in PDAC, we next investigated the abundance and distribution of RBFOX2 protein in resected pancreatic cancers." (PMID 38114498, 2023). "These RBFOX2-mediated exon splicing events occur in pancreatic cancer patients, with differential splicing for a subset of splicing events observed across PDAC sub-types." (PMID 38114498, 2023). "The functional relationship among RBFOX2-mediated exon splicing events warrants further investigation to understand how these splicing events cooperate to promote pancreatic cancer progression." (PMID 38114498, 2023). "In this study, we uncovered a role for RBFOX2 as a tumor suppressor of pancreatic cancer metastasis in mouse models." (PMID 38114498, 2023). "Recent work has identified RBFOX2 as a metastatic suppressor in pancreatic cancer and correlated metastatic progression based on RBFOX2 expression levels and alternative splicing signatures in patient samples." (PMID 37510283, 2023). "In addition, previous study has showed a significant increase RBFOX2 expression in pancreatic cancers compared to normal pancreas, which was consistent with our results." (PMID 38881877, 2024). "We next investigated whether these RBFOX2 target exons are alternatively spliced in pancreatic cancer patients." (PMID 38114498, 2023). "RBFOX2 mediated splicing of ABI1, encoding the Abelson-interactor 1 adapter protein, controls the abundance and localization of ABI1 protein isoforms in pancreatic cancer cells and promotes the relocalization of ABI1 from the cytoplasm to the periphery of migrating cells." (PMID 38114498, 2023). "Based on our prediction of Rbfox2 as a tumor suppressor from our in vivo screen and our observation of decreased RBFOX2 in PDX-derived cell lines from metastatic PDAC, we further investigated the potential role of RBFOX2 downregulation in promoting pancreatic cancer progression." (PMID 38114498, 2023). "Here, we showed RBFOX2 target exons are differentially spliced between normal pancreas and pancreatic cancer, suggesting that alternative splicing of these exons is an integral part of pancreatic cancer progression." (PMID 38114498, 2023). "Utilizing ex vivo and in vivo approaches, we defined a network of RBFOX2-controlled alternative splicing events linked to cytoskeletal remodeling and specifically associated exon-skipping in ABI1 with enhanced migratory potential and enrichment at the cell periphery of pancreatic cancer cells." (PMID 38114498, 2023). "Meanwhile, the deregulation of RBFOX2 (RNA Binding Fox-1 Homolog 2), an RNA-binding protein belonging to the FOX family, facilitates the progression and metastasis of pancreatic cancer through alternative splicing." (PMID 40853971, 2025). "We demonstrate downregulation of RBFOX2, an RBP of the FOX family, promotes pancreatic cancer progression and liver metastasis." (PMID 38114498, 2023). "To further investigate the biological role of RBFOX2-mediated ABI1 exon 9 skipping to promote pancreatic cancer progression, we induced ABI1 splice-switching in Panc1 cells using an ABI1 AON to mimic the ABI1 ∆PSI observed with RBFOX2 knockdown." (PMID 38114498, 2023).
pancreatic cancer (continued). "While insufficient information regarding melanoma was found in the literature, we found that RBFOX2 and HNRNPA2B1 have been established to regulate tumour development—primarily through EMT‐related processes—and in pancreatic cancer, HNRNPA2B1 acts through the ERK/Snail pathway." (PMID 35040264, 2022). "The role of RBFOX2 in directing alternative splicing in pancreatic cancer is not known." (PMID 38114498, 2023). "Overexpression of RBFOX2 in a patient-derived xenograft (PDX) metastatic PDA cell line drastically reduced the metastatic potential of these cells in vitro and in vivo, whereas depletion of RBFOX2 in primary pancreatic tumour cell lines increased the metastatic potential of these cells." (PMID 36949200, 2023).
melanoma (5 papers, 2019 to 2024). A malignant, usually aggressive tumor composed of atypical, neoplastic melanocytes. "Although in melanoma the presence of the retinoblastoma binding (RB) mRNA Rbfox2 in SGs was associated with progression and metastasis, the presence of TIA1, G3BP1, and TIAL1 in melanoma-derived SGs has not been reported, so new experimental approaches would be needed." (PMID 39594467, 2024). "Higher levels of RBFOX2 have been significantly associated with low response and poor prognosis in patients with non-small cell lung cancer (NSCLC) and melanoma who receive immunotherapy." (PMID 38881877, 2024). "In melanoma, SGs mediate RNA binding fox-1 homolog 2 (RBFOX2) localization and further promote retinoblastoma 1 (RB1) protein levels along with mRNA expression, thus significantly promoting melanoma cell metastasis and tumor growth." (PMID 37179344, 2023). "To investigate the effect of resveratrol-mediated suppression of SG-mediated Rbfox2 localization on cancer progression, we used a B16-F10 murine melanoma model." (PMID 31028247, 2019). "Treatment with resveratrol prevented the migration of Rbfox2 from the nucleus to the cytoplasm and significantly reduced tumor growth in a mouse model of melanoma." (PMID 31028247, 2019). "Our findings supported our hypothesis, we discovered a notable association between elevated expression levels of RBFOX2 and decreased response to treatment, along with unfavorable progression-free survival (PFS) outcomes in patients with advanced NSCLC and melanoma who received immunotherapy." (PMID 38881877, 2024). "Additionally, resveratrol treatment inhibited SG-mediated Rbfox2 localization, further inhibiting RB1 protein expression, and inhibited specific Rbfox2 localization to the cytoplasm in melanoma B16-F10 cells, thereby effectively inhibiting metastasis and tumor growth ability." (PMID 31028247, 2019).
colon cancer (4 papers, 2008 to 2024). "Despite previous study and our results found that the downregulation of RBFOX2 mRNA in colorectal cancer tissue compared to normal tissue in the colon cancer TCGA data, RBFOX2 protein expression was found to be upregulated in colorectal cancer." (PMID 38881877, 2024). "Although we observed nuclear localization of Rbfox2 in cells from normal colon tissue, we observed strong cytoplasmic staining of Rbfox2 in different regions of cells from colon cancer tissue." (PMID 31028247, 2019). "In this study, we confirmed that Rbfox2, which is present in the nucleus as a splicing regulator, localizes to the cytoplasm of human colon cancer tissues and that induction of Rbfox2 dissociation from SGs by resveratrol treatment inhibits cancer progression." (PMID 31028247, 2019). "Immunofluorescence microscopy revealed that Rbfox2 exhibited nuclear localization in normal tissue but exhibited cytoplasmic localization in human colon cancer tissue." (PMID 31028247, 2019). "Most colon cancer tissues displayed low RB1 protein levels relative to normal colon tissues, whereas Rbfox2 levels in colon cancer tissue were significantly higher than those in normal colon tissue." (PMID 31028247, 2019). "Additionally, we observed that Rbfox2 localized to the cytoplasm of human colon cancer cells and that RB1 protein levels were very low in human colon cancer tissue." (PMID 31028247, 2019). "Additionally, we observed significantly lower RB1 protein levels in human colon cancer tissues than in normal tissues and found that Rbfox2 plays an important role in cell cycle progression, regardless of cellular stress." (PMID 31028247, 2019). "The localization of Rbfox2 in normal colon and colon cancer tissues was quantified." (PMID 31028247, 2019). "Rbfox2 levels were elevated in colon cancer tissue relative to normal colon tissue, whereas RB1 protein levels were lower in cancer tissue." (PMID 31028247, 2019).
congenital heart disease (4 papers, 2016 to 2024). "RBFOX2 deficiency is observed in congenital heart defects such as hypoplastic left heart syndrome, disease development in diabetic hearts, and CHD that co-occurs with extracardiac congenital anomalies and neurodevelopmental disabilities." (PMID 39684734, 2024). "Mutations or dysregulation of RBFOX2 are associated with congenital heart defects as well as other pathologies." (PMID 39684734, 2024). "The mutations of RBFOX2 are associated with congenital heart disease and neuro developmental disabilities." (PMID 28316886, 2017). "RBFOX2 is dysregulated in diabetic hearts and in a study of parent-offspring trios with congenital heart disease (CHD), RBFOX2 was one of the genes identified as contributing to the extracardiac congenital anomalies and neurodevelopmental disabilities." (PMID 39684734, 2024). "To determine regulators that account for abnormal gene expression in HLHS patient RVs, we focused on the RNA binding protein Rbfox2, because it was identified as a major risk allele for HLHS using a large cohort of congenital heart disease patients." (PMID 27485310, 2016).
endometrial cancer (4 papers, 2023 to 2024). Primary or metastatic malignant neoplasm involving the endometrium (mucous membrane that lines the endometrial cavity). "It was reported that circRAPGEF5 interacts with and inhibits the splicing regulator RNA-binding protein fox-1 homolog 2 (RBFOX2) to confer ferroptosis resistance by modulating the alternative splicing of TFRC in endometrial cancer cells." (PMID 37686142, 2023). "It was found that in endometrial cancer, circRAPGEF5 acts with RNA binding fox-1 homolog 2 (RBFOX2) to block the binding of RBFOX2 to pre-mRNA and inhibit TFRC expression." (PMID 37152286, 2023). "For example, circRAPGEF5 medicated ferroptosis by modulating alternative splicing of TFRC in endometrial cancer, and circRAPGEF5/RBFOX2 axis might be a cancer therapy target." (PMID 39170701, 2024). "Moreover, circRAPGEF5 was reported to change the splicing of TFRC by binding to and inhibiting RBFOX2 and then inhibiting iron uptake to repress the ferroptosis of endometrial cancer cells." (PMID 37686142, 2023).
gastric cancer (4 papers, 2020 to 2024). A primary or metastatic malignant neoplasm involving the stomach. "Furthermore, our study is consistent with another study that found high levels of RBFOX2 was associated with worse survival in gastric cancer patients." (PMID 38881877, 2024). "RBFOX2 was overexpression and promoted the migration of gastric cancer cells, which was consistent with what we have found that RBFOX2 was high in STAD tissues than normal tissues." (PMID 38881877, 2024). "Notably, CELF2, RBFOX2, PTBP2 and QKI were also involved in the misregulation of AS events in Epstein-Barr virus-associated gastric carcinomas." (PMID 33186122, 2020).
hypoplastic left heart syndrome (4 papers, 2023 to 2025). Hypoplastic left heart syndrome (HLHS) refers to the abnormal development of the left-sided cardiac structures, resulting in obstruction to blood flow from the left ventricular outflow tract. "A previous study identified a genetic variant in the AS factor Rbfox2 associated with hypoplastic left heart syndrome (HLHS), a condition wherein the left ventricle does not form correctly and cannot adequately support systemic circulation." (PMID 39773891, 2025). "In contrast, in hypoplastic left heart syndrome (HLHS), RBFOX2 is primarily cytoplasmic in the hearts of HLHS patients." (PMID 39243148, 2024).
leukaemia (4 papers, 2023 to 2025). "RBFOX2 is also required for self-renewal of leukaemia stem/initiation cells and acute myeloid leukaemia maintenance." (PMID 37640841, 2023). "Altogether, these results suggest that depletion of RBFOX2 promotes myeloid differentiation exclusively in leukaemia." (PMID 37640841, 2023). "In MLL-AF9 (MA9) leukaemia mice, KD of Rbfox2 greatly inhibited colony-forming capacity of leukaemic bone marrow blast cells, reduced LSC population and promoted their differentiation, suggesting RBFOX2 is required for LSC/LIC maintenance." (PMID 37640841, 2023). "A study utilising the GEO database (GSE13159) revealed that AML patients across various subtypes, including normal karyotype, mixed lineage leukaemia and t(15:17), exhibited significantly elevated RBFOX2 expression in bone marrow samples compared to healthy counterparts." (PMID 39243148, 2024). "We consistently observed a reduced leukaemia burden, which might be attributed to the promotion of differentiation resulting from RBFOX2 depletion." (PMID 37640841, 2023). "Therefore, RBFOX2 is identified as a chromatin factor that facilitates m6A deposition on caRNAs during locus-specific chromatin regulation with therapeutic implications in leukaemia." (PMID 37640841, 2023). "In AML, this RBFOX2/m6A/RBM15/YTHDC1/PRC2 axis is essential for leukemia cell survival, proliferation, and the self-renewal and maintenance of leukemia stem/progenitor cells." (PMID 41403702, 2025). "RBFOX2 is essential for the self‐renewal and stemness maintenance of AML cells, making it a potential target for leukaemia treatment." (PMID 39243148, 2024). "Collectively, these results suggest that RBFOX2 is required for AML cell survival and leukaemia maintenance, which it may facilitate by promoting LSC/LIC self-renewal and inhibiting AML cell differentiation." (PMID 37640841, 2023).
Ataxia (3 papers, 2012 to 2025). Ataxia refers to impaired coordination of voluntary muscle movement. "While the isolated knockout of RBFOX1 or RBFOX2 causes minimal cortical malformation due to functional redundancy, RBFOX1 KO mice exhibit increased seizure susceptibility, and RBFOX2 KO leads to cerebellar defects and ataxia." (PMID 41303558, 2025).
autism (3 papers, 2016 to 2020). Persistent deficits in social interaction and communication and interaction as well as a markedly restricted repertoire of activity and interest as well as repetitive patterns of behavior. "Besides, the Shank gene family members, as a potential target of RBFOX2, play an important part in neuronal functions, where alterations in the encoded proteins may be connected to autism." (PMID 33179042, 2020). "Finally, three CvI-unique are also registered in the Autism KB database: Htr2c, Rbfox2 (an RNA binding protein), and Txk (a tyrosine kinase)." (PMID 27782041, 2016).
cardiomyopathy (3 papers, 2023 to 2024). A disease of the heart muscle or myocardium proper. "Several RBPs, including RBM20 and RBFOX2, are associated with human cardiomyopathies." (PMID 38535111, 2024). "The following sections will discuss the recent understanding of well-characterized RBPs, including RBM20, RBM24, RBPMS, RBPMS2, RBFOX1, RBFOX2, and several readers of mRNA methylation, such as IGF2BP2 and YTHDC1, associated with cardiomyopathy in humans and/or animal models." (PMID 38535111, 2024).